SEMA3C (semaphorin 3C)
Diseases named in the same sentence as SEMA3C in open-access papers (continued):
Sharing a sentence is not in itself a finding about the gene and the disease.
pancreatic cancer (continued). "NRP1 are not only expressed in pancreatic cancer but also in macrophages/monocytes, this suggests that SEMA3C could affect the macrophage polarization by binding the NRP1 expressed in macrophages." (PMID 35785187, 2022). "We next explored the function of SEMA3C in pancreatic cancer." (PMID 35785187, 2022). "SEMA3C may also be involved in promoting resistance of pancreatic tumors to gemcitabine, a nucleoside analog used as a chemotherapy medication in pancreatic cancer." (PMID 30759745, 2019). "A previous study found that SEMA3C depletion reverses the process of EMT in pancreatic cancer." (PMID 31649890, 2019). "SEMA3C was reported as an oncogene and could support the tumor progression in pancreatic cancers." (PMID 35785187, 2022). "In addition, SEMA3C inhibition sensitized KRAS or MEK1/2 inhibition in pancreatic cancer cells." (PMID 35785187, 2022). "In vitro experiments showed that SEMA3C promotes proliferation, invasion, and EMT of pancreatic cancer cells through activation of the ERK1/2 signaling pathway." (PMID 38321460, 2024). "We also demonstrated the synergistic effect in killing pancreatic cancer cells with the combination of MEK inhibitor and SEMA3C inhibitor." (PMID 35785187, 2022). "AHNAK2, ARL4C, ASAP2, SEMA3C were identified as being highly expressed in both KRAS G12D cell lines and pancreatic cancer patients." (PMID 35785187, 2022). "SEMA3C was highly expressed in pancreatic cancers, especially in cells and patients with high KRAS G12D expression, and high SEMA3C expression was enriched in the signaling pathways upregulated by KRAS." (PMID 35785187, 2022). "In line with this, preliminary unpublished work in our laboratory has shown that attenuation of SEMA3C signalling dampens cell proliferation and oncogenic cell signalling in panel of KRAS mutant pancreatic cancer cell lines." (PMID 30759745, 2019). "Knockdown of SEMA3C attenuates the proliferation, migration, invasion, and EMT in pancreatic cancer cell lines." (PMID 31649890, 2019). "Moreover, higher levels of Sema3C protein induced prostate tumor growth and inhibited apoptosis by transactivating multiple receptor tyrosine kinases via PlexinB1 and NRP1 interaction, as well as increased progression of pancreatic cancer through extracellular signal-related kinase (ERK) signaling." (PMID 31726800, 2019).
lung carcinoma (8 papers, 2017 to 2024). "SEMA3C is a protein that has been implicated in various aspects of cancer development and progression and is overexpressed in several types of cancer, including breast, prostate, and lung cancer." (PMID 37443749, 2023). "In mice, SEMA3C overexpression in lung cancer cell lines significantly enhanced the ability of tumor cells to metastasize." (PMID 36277723, 2022). "In many cancers including lung cancer, increased SEMA3C expression is related to unfavorable prognosis and tumor progression." (PMID 35437508, 2022). "Shortly after the seminal work on SEMA3C in development in the early 1990s, recognition of SEMA3C for its roles of in carcinogenesis began to surface in a variety of different cancer types beginning with ovarian and lung cancer." (PMID 30759745, 2019). "In lung cancer, increased SEMA3C expression is a marker of EMT." (PMID 30759745, 2019).
Obesity (6 papers, 2020 to 2025). Accumulation of substantial excess body fat. "Among, relatively, recently identified adipokines, visfatin, chemerin, apelin, and semaphorin 3 C (SEMA3C) are reported to be associated with obesity and T2DM." (PMID 32561824, 2020). "Moreover, mRNA expression of SEMA3C in adipose tissue was associated with insulin sensitivity, suggesting pathophysiological roles in human obesity and metabolic deterioration." (PMID 32561824, 2020). "The NGS analysis revealed four variants related to obesity: SIM1, SEMA3C, PLXNA4, and CREBBP gene mutations." (PMID 40428410, 2025). "Based on these, SEMA3C can be suggested as a potent molecule which participates in the pathophysiology in obesity and metabolism." (PMID 32561824, 2020). "Prominent among the elevated obesity-associated circulating adipokines and cytokines are the C-reactive protein (CRP), Semaphorin-3C (Sema3C), Tumor Necrosis Factor-alpha (TNF alpha), Interleukin-6 (IL-6), Monocyte Chemoattractant Protein-1 (MCP1), and Interleukin-8 (IL-8)." (PMID 38068748, 2023). "FA treatment decreased mRNA of ApoD, SEMA3C, CXCL12, and sFRP2, which are closely related to adipocyte differentiation and obesity." (PMID 33915783, 2021).
neuroblastoma (5 papers, 2018 to 2021). Neuroblastoma (NB) is the most common solid, extracranial childhood tumor. "Semaphorin 3C downregulation was reported to be associated with a more metastatic phenotype in neuroblastoma cells, consistent with our present findings of increased B0404 melanoma cell invasion and migration." (PMID 34926249, 2021). "Semaphorin 3C (SEMA3C) has been reported to play a pivotal role in tumor microenvironment driven neuroblastoma metastasis and progression." (PMID 33614471, 2020). "Conversely, Valerie Castellani's team found that neuroblastoma dissemination is induced by the shutdown of SEMA3C, which constrains the tumoral mass of neuroblastoma." (PMID 31649890, 2019). "In contrast to epithelial cancers, Sema3C serves as a cohesion cue in neuroblastoma." (PMID 29642487, 2018). "Downregulation of either Sema3C or its receptor PlexinA4 induces neuroblastoma dissemination." (PMID 29642487, 2018). "As seen in neuroblastoma, Sema3C may be tumor-suppressive and suppress metastasis." (PMID 29642487, 2018). "In addition, it was found that SEMA3C could restrict the metastatic spread of neuroblastoma." (PMID 31649890, 2019).
acute kidney injury (4 papers, 2023 to 2024). Sudden and sustained deterioration of the kidney function characterized by decreased glomerular filtration rate, increased serum creatinine or oliguria. "Recently, it was shown that SEMA3C plays an important role in the development of murine acute kidney injury by promoting vascular permeability, interstitial edema, leukocyte infiltration and tubular injury." (PMID 37893159, 2023). "Sema3c knockout mice display decreased renal tissue damage and leukocyte infiltration following acute kidney injury." (PMID 37580336, 2023). "SEMA3C is a secreted glycoprotein, which may promote microvascular permeability in acute kidney injury." (PMID 37460555, 2023). "However, after surgically induced acute kidney injury Sema3c expression is upregulated as compared to control uninjured kidneys." (PMID 37580336, 2023). "Furthermore, the kinetics of SEMA were related to sepsis complications; SEMA3A, SEMA3C, SEMA3F, and SEMA4D were related to respiratory failure; SEMA3C and SEMA7A were related to acute kidney injury, while SEMA3C and SEMA3F were related to septic shock." (PMID 39770766, 2024).
astrocytoma (4 papers, 2015 to 2021). "Our study for the first time examined Sema3C expression at protein levels in astrocytoma tissues of different malignancy grade." (PMID 26032848, 2015). "In previous studies, we found that accumulated high SEMA3C protein levels, which did not correlate with mRNA levels, were related to the clinicopathological characteristics of astrocytoma patients." (PMID 33036421, 2020).
cervical cancer (4 papers, 2019 to 2022). A primary or metastatic malignant neoplasm involving the cervix. "We aimed to analyze SEMA3C expression in cervical cancer and investigate the role of SEMA3C in cervical cancer and its underlying mechanism, which is important for exploring new therapeutic targets and prognostic factors." (PMID 31649890, 2019). "To reveal clinicopathologic variables associated with poor survival in cervical cancer, we first performed a univariate analysis, which revealed that SEMA3C expression correlated significantly with poor OS." (PMID 31649890, 2019). "To identify SEMA3C-associated signaling pathways in cervical cancer, we conducted Gene Set Enrichment Analysis (GSEA) between high and low SEMA3C expression data sets." (PMID 31649890, 2019). "Though the activation of the p-ERK pathway, SEMA3C promotes cervical cancer growth, which is related to poor prognosis." (PMID 35237609, 2021). "Materials and Methods: The expression of SEMA3C was examined in paraffin-embedded cervical cancer specimens." (PMID 31649890, 2019). "In the CCK-8 assay, SEMA3C depletion significantly attenuated the proliferation of cervical cancer cells." (PMID 31649890, 2019). "In the present study, we aimed to analyze the mRNA and protein expression levels of SEMA3C in cervical cancer tissues and investigate the impact of SEMA3C on cancer cell growth and signal pathway activation." (PMID 31649890, 2019). "The present study showed that the knockdown of SEMA3C in cervical cancer reduced the proliferative capacity of cervical cancer cells in vitro and in vivo." (PMID 31649890, 2019). "Silencing of SEMA3C suppressed cervical cancer cell proliferation, colony formation ability, and the activation of the p-ERK signaling pathway in vitro." (PMID 31649890, 2019). "To illustrate the effect of SEMA3C on cervical cancer cell proliferation, we silenced SEMA3C in HeLa and SiHa cells with two different siRNAs (siSEMA3C-1 and siSEMA3C-2), and their knockdown efficiency was verified by immunoblot analyses." (PMID 31649890, 2019). "Both the mRNA level and protein level of SEMA3C in cervical cancer tissues were found to be similar to those in normal cervical tissues." (PMID 31649890, 2019). "In this study, we first investigated SEMA3C expression in cervical cancer using 12 pairs of cervical cancer tissues and adjacent normal tissues." (PMID 31649890, 2019). "We examined SEMA3C expression in four cervical cancer cell lines using western blotting, and found that SEMA3C protein levels were higher in HeLa and SiHa cell lines." (PMID 31649890, 2019). "The ERK signaling pathway, which is activated by SEMA3C in cervical cancer, is a well-known signaling cascade that transmits signals from cell surface receptors to promote proliferation and survival programs in a high percentage of tumors, including cervical cancer." (PMID 31649890, 2019). "In the present study, we explored the possible role of SEMA3C in cervical cancer." (PMID 31649890, 2019). "In summary, SEMA3C expression may be a potential prognostic molecular marker of poor survival in cervical cancer patients." (PMID 31649890, 2019). "We also evaluated SEMA3C expression by IHC in 87 human cervical cancer samples." (PMID 31649890, 2019). "We found that SEMA3C promotes cervical cancer cell proliferation, which could partially account for decreased survival." (PMID 31649890, 2019). "SEMA3C may activate the p-ERK signaling pathway to promote the proliferation of cervical cancer cells." (PMID 31649890, 2019). "Therefore, the combination of inhibitors of SEMA3C or associated PLEXIN/NRP receptors and RTK inhibitors could represent a new therapeutic strategy to improve the therapeutic outcome of cervical cancer." (PMID 31649890, 2019). "SEMA3C might be a new therapeutic target for preventing cervical cancer." (PMID 31649890, 2019). "Thus far, the role of SEMA3C in cervical cancer remains unknown." (PMID 31649890, 2019).
cervical cancer (continued). "Mechanically, to explore whether solamargine regulates the Erk pathway by targeting a specific mRNA, we selected genes reported in recent years to regulate the Erk pathway in cervical cancer, including PBK, RACK1, CXCL3, TRIP4, and SEMA3C, for study." (PMID 36345403, 2022). "To investigate whether SEMA3C promotes cervical cancer growth via the Ras/Raf/ERK pathway, we silenced SEMA3C with siSEMA3C-1 and siSEMA3C-2 and observed remarkably decreased levels of p-ERK." (PMID 31649890, 2019). "In order to investigate whether solamargine regulates the Erk signaling pathway by modulating target mRNAs, we screened out genes that regulate this pathway in cervical cancer including PBK, RACK1, CXCL3, TRIP4, and SEMA3C, which have been reported in the literature in recent years." (PMID 36345403, 2022).
endometriosis (4 papers, 2015 to 2024). The growth of functional endometrial tissue in anatomic sites outside the uterine body. "ACKR1, LMNB1, MFAP4, NMU, and SEMA3C were upregulated in ectopic endometrial tissues of patients with endometriosis compared with normal endometrium (P < 0.001), which was consistent with the results of bioinformatics analysis." (PMID 36277723, 2022). "Q RT-PCR was used to detect the expression of ACKR1, LMNB1, MFAP4, NMU, and SEMA3C mRNA in ectopic endometrial tissues of patients with endometriosis." (PMID 36277723, 2022). "Interestingly, SEMA3A and SEMA3C expression is markedly increased in women with endometriosis." (PMID 38541683, 2024).
liver fibrosis (3 papers, 2022 to 2024). "Moreover, we identified distinct mechanisms underlying Sema3C-mediated activation of HSCs within the TME compared to liver fibrosis." (PMID 38956074, 2024). "SEMA3C regulates extracellular matrix composition through increased expression of IL-6, transforming growth factor-β (TGF-β) and connective tissue growth factor (CTGF), and was implicated in the development of liver fibrosis." (PMID 37893159, 2023). "Deletion of either SEMA3C or its receptor NRP2 in activated HSCs reduced liver fibrosis in mice." (PMID 36551769, 2022). "Liver and serum SEMA3C expressions correlate with liver fibrosis in CHC." (PMID 36551769, 2022).
bladder cancer (2 papers, 2018 to 2024). "High SEMA3C expression was associated with poor overall survival in renal clear cell carcinoma and bladder carcinoma." (PMID 29348142, 2018). "This study, on the other hand, is a preliminary investigation of the potential role of sema3C and sema4A in bladder cancer." (PMID 39457718, 2024). "To the best of our knowledge, sema3C and sema4A have never been studied among patients with bladder cancer, so we are the first to report on this matter." (PMID 39457718, 2024). "Similar to sema3C, sema4A has never been studied in bladder cancer." (PMID 39457718, 2024).
breast tumor (2 papers, 2017 to 2023). "Nevertheless it has been recently demonstrated that ADAMTS1 promotes breast tumor cell migration by regulating the release of semaphorin 3c from the ECM." (PMID 28173833, 2017).
dyslexia (2 papers, 2021 to 2025). A learning disorder characterized by an impairment in processing written words. "Due to its roles in brain development, SEMA3C represents a convincing candidate gene for susceptibility to dyslexia, a cognitive trait which has been associated with changes in cerebral cortical architecture." (PMID 34076780, 2021). "We thus propose SEMA3C as a candidate gene for dyslexia susceptibility." (PMID 34076780, 2021). "Instead, we found that two relatively rare (MAF ~ 0.01) noncoding variants within the first intron of the gene SEMA3C, predicted to have a functional impact, were present in all but two family members with dyslexia, while being absent from all unaffected members." (PMID 34076780, 2021).
head and neck squamous cell carcinoma (2 papers, 2023 to 2024). A squamous cell carcinoma that arises from any of the following anatomic sites: lip and oral cavity, nasal cavity, paranasal sinuses, pharynx, larynx, and salivary glands. "The analysis presented in the study here identified SEMA3C as significantly upregulated in pancreatic, bile duct, stomach, and head and neck squamous cell carcinoma, which was correlated with worse overall survival." (PMID 37719704, 2023).
hepatocellular carcinoma (2 papers, 2024 to 2025). A malignant tumor that arises from hepatocytes. "Sema3C has recently been studied as a novel biomarker in Hepatocellular carcinoma (HCC), where NRP1 and Integrin Beta1 (ITGβ1) act as functional receptors of Sema3C which activates Serine threonine Kinase (AKT)/GLI Family Zinc Finger 1 (Gli1)/c-Myc signaling pathways leading to tumor initiation." (PMID 40277760, 2025).
Hirschsprung disease (2 papers, 2019 to 2024). Hirschsprung disease (HSCR) is a congenital intestinal motility disorder that is characterized by signs of intestinal obstruction due to the presence of an aganglionic segment of variable extent in the terminal part of the colon. "Similarly, SEMA3C (Semaphorin 3C) gene variants have been linked to the regulation of the enteric nervous system in rodents and rare cases of Hirschsprung’s disease in humans." (PMID 39570887, 2024).
Insulin resistance (2 papers, 2022 to 2023). Increased resistance towards insulin, that is, diminished effectiveness of insulin in reducing blood glucose levels. "However, the association between semaphorin 3C and insulin resistance, and the mechanism of exercise induced decreases in semaphorin 3C levels is poorly understood unknown." (PMID 37576981, 2023). "The downregulation of semaphorin 3C levels following HIFT intervention in our study led to significant decreases in insulin resistance." (PMID 37576981, 2023). "The expression of semaphorin 3C correlates with weight change, and WAT expression decreased after weight loss through bariatric surgery, while semaphorin 3C can contribute to insulin resistance and type 2 diabetes." (PMID 37576981, 2023). "Moreover, SEMA3C expression correlated with body weight, insulin resistance and adipose tissue morphology." (PMID 36551769, 2022).
liver cancer (2 papers, 2022 to 2024). An epithelial or non-epithelial malignant neoplasm that arises from the liver. "In the future, different liver cancer models will be used to verify the role of Sema3C in diverse etiologies of HCC, such as the hydrokinetic tail vein (HTV) -NRasV12+Myr-AKT proto-oncogene driven HCC tumors and non-alcoholic steatohepatitis (NASH)-HCC mouse models." (PMID 38956074, 2024).
oral cancer (2 papers, 2018 to 2019). "However, our finding of upregulation of SEMA3C is not consistent with an earlier report on oral cancer." (PMID 31796082, 2019).
prostate adenocarcinoma (2 papers, 2018 to 2023). "SEMA3C expression is correlated with expression of steroidogenic enzymes CYP11A1 and SRD5A2 as well as the AR target gene, FKBP5, in prostate adenocarcinoma patients according to TCGA PanCancer dataset available on cBioPortal." (PMID 37800655, 2023).
Sepsis (2 papers, 2024 to 2025). Sepsis is defined as life-threatening organ dysfunction caused by a dysregulated host response to infection. "In our sepsis cohort, SEMA kinetics were linked to sepsis complications with SEMA3A, SEMA3C, SEMA4D and SEMA7A associated with mortality." (PMID 40869413, 2025). "Patients with sepsis had significantly higher serum levels of SEMA3C, SEMA3F, SEMA4D, and SEMA7A and a significantly lower SEMA3A." (PMID 39770766, 2024). "Other class 3 semaphorins, such as SEMA3C, were increased in patients with sepsis, correlated with the WBC, neutrophil, and lymphocyte counts, and showed different serum kinetics in survivors who had a significant decrease in serum concentrations on day 5, in contrast to non-survivors." (PMID 39770766, 2024). "While SEMA3A was decreased, SEMA3C, SEMA3F, SEMA4D, and SEMA7A were increased in sepsis patients, and all analyzed SEMA showed good accuracy in identifying patients with sepsis." (PMID 39770766, 2024). "In conclusion, we have shown that patients with sepsis have different serum concentrations of SEMA3A, SEMA3C, SEMA3F, SEMA4D, and SEMA7A compared to healthy controls and that their kinetics during sepsis correlate with disease severity and outcomes." (PMID 39770766, 2024). "While SEMA3A was decreased, SEMA3C, SEMA3F, SEMA4D, and SEMA7A were increased in sepsis patients." (PMID 39770766, 2024).
atrial septal defect (1 paper, 2025). Interauricular communication is a congenital malformation characterized by a communication between the atrial chambers of the heart. "Variants in genes associated with atrial septal defects and ventricular septal defects (e.g., DOCK6, EOGT, EP300, EVC, EVC2, and SEMA3C) have also been identified in patients." (PMID 41153298, 2025).